TLR1 (toll like receptor 1)
Diseases named in the same sentence as TLR1 in open-access papers (continued):
Sharing a sentence is not in itself a finding about the gene and the disease.
infection (continued). "Once internalized, mycobacterial specific N-glycolyl MDP is recognized and activates NOD2, leading to synergistic interactions with TLRs and TLR heterodimers (TLR2, TLR1, and TLR6) to promote downstream activation of NF-κB signaling and a pro-inflammatory response to infection." (PMID 34485444, 2021). "The variant was a cis-eQTL for IFNB1 after activation of the TLR1/TLR2, TLR4, and TLR7/TLR8 pathways, but not after infection with an influenza virus." (PMID 33147208, 2020). "Infections with mice lacking either TLR1 or TLR6, the known co-receptors for TLR2, did not present with the same disease phenotype as TLR2−/− mice, suggesting that neither is crucial for the TLR2-mediated control of infection with L. major or L. mexicana." (PMID 27716391, 2016). "As the disease kinetics in TLR1−/− or TLR6−/− mice do not match that of TLR2−/− mice, this strongly suggests that the role for TLR2 during infection does not require either TLR1 or TLR6." (PMID 27716391, 2016). "In addition, the expression levels of TLR1, TLR2, TLR7, and TRAF3 were significantly increased in response to GPV and H9N2 infection." (PMID 27916934, 2016). "Moreover, we observed a highly positive correlation between viral replication and host mRNA expressions of TLR1-5 and 7, AvBD4-6, 10, and 12, all the cytokines measured, MHC class I, FAS ligand, and iNOS, mainly at 72 h post-infection." (PMID 27757109, 2016). "Since activation of nfkbiz and il6 is not attenuated after infection with a PorB-deficient MC58 strain, signal transduction initiated by TLR2/TLR1 does not seem to play a major role in HIBCPP cells, at least for stimulation of the IκBζ-IL6 axis." (PMID 25347003, 2014). "Therefore, we analyzed the expression of TLR15, TLR1 and TLR2 genes after infection of HD11 macrophages with live Mycoplasma synoviae for 1, 6 or 24 h." (PMID 24134665, 2013). "Tlr1 mRNA decreased rapidly in Sf9 cells after baculovirus infection and was undetectable 4d after infection, paralleling the observed decrease in secretion of the DSP-PP240 processing activity after infection." (PMID 22815932, 2012). "MRNA levels of genes encoding for chemokines (CXCL1 and CXCL5), cytokines (IL-10, IL-15 and IL-32), pattern recognition receptors (TLR1) and innate signaling molecules like IRAK3 and TRAF6, were all increased after MVA-C infection in comparison with MVA-WT-infected cells." (PMID 22536391, 2012). "We have identified two structurally related lipopeptides without TLR-signaling capacity that also modulate RSV infection, whereas Pam3CSK4-reminiscent TLR1/2 agonists did not, and conclude that modulation of infection is independent of TLR activation." (PMID 20808895, 2010). "The survival rate of these mice infected i.n. with LVS was indistinguishable from the survival rate of control mice indicating that neither TLR1 nor TLR6 is exclusively required for host resistance to LVS infection." (PMID 19936231, 2009). "At this infection stage, ALV-J may be recognized by TLR1, TLR7 and TLR15." (PMID 30841905, 2019). "Indeed, it was shown that L. (Viannia) panamensis infection results in up-regulation of TLR1, TLR2, TLR3, and TLR4 expression, inducing activation of infected macrophages, whereas infection with L. donovani suppresses the TLR2–NF-κB–mediated pro-inflammatory cytokine response." (PMID 24098824, 2013). "Moreover, signaling through TLR2 does not depend exclusively on TLR1 or TLR6 during F. tularensis LVS infection." (PMID 19936231, 2009). "Similarly, E. coli K88 and mycotoxin zearalenone (ZEA) infection of IPEC-1 epithelial cell line was protected in the presence of mixed Lactobacillus strains (L. acidofilus ID11692, L. plantarum ID1253 and L. paracasei ID13239) by downregulating TLR-1, TLR-2 and TLR-4 gene expression." (PMID 32045425, 2020).
infection (continued). "On the other hand, early after infection, compared to noninfected pigs, expression of GNLY and CSF3 but also that of TLR1, 3, and 6, key players of innate response development, was downregulated only in HS pigs." (PMID 36629432, 2023). "In line with the SISP model, the mRNA expression of TLR1, -3, -4, -6, -7 (not detected), and -9 was unaffected by either HB101 or C83901 infection in IPEC-J2 cells." (PMID 31221216, 2019). "The mRNA expression of TLR1, TLR2, TLR4 and TLR6 of C. burnetii NM stimulated PBMCs derived from naive and infected goats at day 35 equalled the expression as prior infection (data not shown)." (PMID 25279829, 2014). "In addition to LPS, the rs12553564 variant was found to be an eQTL for IFNB1 in monocytes activated by Pam3CSK4 (targeting the TLR1/TLR2 receptors) and R848 (targeting the TLR7/TLR8 receptors), but not after infection with an influenza virus." (PMID 33147208, 2020). "Due to our inability to exclude redundancy between TLR1 and TLR6 in these infection models, we are unable to rule out the possibility that TLR2 may utilise either TLR1 or TLR6 co-receptor involvement in these settings." (PMID 27716391, 2016).
tumor (65 papers, 2012 to 2026). "We orthogonally replicated the iTME-specific associations of LSP1 and TLR1 to BrCa risk using patient tumor biopsies and comparative mapping, respectively." (PMID 37664640, 2023). "We also observed that fewer tumor-infiltrating cytotoxic T lymphocytes were located within the tumor microenvironment in patients bearing the TLR1-N248S polymorphism." (PMID 37945630, 2023). "TLR2 along with TLR1 or TLR6 on tumor-associated microglia mediates an immunosuppressive role by enhancing production of matrix metalloprotease (MMP) to facilitate tumor invasion." (PMID 33520994, 2020). "Ten tumor-exclusive mutations were observed, including TLR1 rs5743618, present in 100% of tumors." (PMID 41816790, 2026). "Additionally, the density of tumor-infiltrating CD8+ T cells was significantly lower in locally advanced stage III COAD patients bearing the TLR1-N248S polymorphism." (PMID 37945630, 2023). "The TLR1-N248S polymorphism might reduce the ability of immunogenic chemotherapeutic agents to reshape the tumor microenvironment, leading to an insufficient antitumor immune response and tumor recurrence." (PMID 37945630, 2023). "Furthermore, patients carrying the TLR1-N248S polymorphism had fewer tumor-infiltrating CD8+ lymphocytes within the TME in locally advanced COAD and associated with poor DFS." (PMID 37945630, 2023). "The study also revealed that TLR1/2-mediated co-stimulation enhanced antitumor CD8+ T cell function when encountering tumor cells, further supporting the potential for leveraging TLR1/2 signaling in immunotherapeutic strategies." (PMID 40948803, 2025). "Adoptive transfer of TLR1/2 and 41BB agonist (3H3) treated pmel transgenic T cells into B16-F1 melanoma bearing mice resulted in improved tumor rejection and survival, highlighting that TLR signaling within CD8+ T cells can boost antitumor immunity." (PMID 40948803, 2025). "Studies in colorectal cancer have demonstrated that transfection with miR-29b mimics can target the 3’UTR of TLR1/7/8, inhibit their expression, reduce IL-6 secretion, and reverse Treg-mediated immunosuppression, indicating its tumor-suppressive role." (PMID 41488647, 2025). "In tumor models of lung cancer, leukemia, and melanoma, TLR1/2 antagonists suppress the inhibitory function of Foxp3+ Tregs, enhance the cytotoxicity of tumor-specific CTLs, and lead to the depletion of tumor-infiltrating Treg cells." (PMID 41488647, 2025). "The anti-tumor effect of activating TLR1/2 was shown to be a consequence of the reciprocal modulation of effector T cells (Teff) and regulatory T cells (Treg)." (PMID 37112730, 2023). "Their in vivo study showed that treatment with bacterial lipoprotein (BLP), a TLR1/2 agonist, decreased tumor growth in the lung LLCI C57BL/6 mouse model compared to control mice." (PMID 37112730, 2023). "Tumor volume and TLR1, BCL-2, Cyclin D1 and survivin protein levels were significantly reduced in the combined treatment group with miR-15a + RT or miR16 + RT compared to control or single modality treatment." (PMID 37112730, 2023). "Based on this approach, we found two genes (Trim5 and Tlr1) correlated with the increased tumor phenotype of the GM:F344 group." (PMID 37458451, 2023). "These genes included those related to P/DAMP signaling (e.g., Il6, Tlr1, Tlr4, Il1b, Il18), necroptotic tumor cell death (e.g., Casp1, Casp8, Il1b), and activation of the adaptive immune system (e.g., Cd80, Cd8a, Ccr5, Cxcl10)." (PMID 37213298, 2023). "This study showed that TLR1/2 increased FcgR IV expression in macrophages, which led to Treg cell depletion and augmentation of T cell/Treg ratios within the tumor." (PMID 35309296, 2022). "The finding that TLR1 expression correlates with immune cell markers suggests that TLR1 can regulate tumor immunity in LGG." (PMID 34869584, 2021).
tumor (continued). "Priming with CpG attenuated Il6 and Nlrp3 expression, further upregulated expression of Nod2, Oas2, RhoA, Pycard, Tlr1/2 and Il12, and enhanced T-cell number and activation while polarizing macrophages to an anti-tumor phenotype." (PMID 33441763, 2021). "The expression of TLR-1 was significantly correlated with advanced tumour–node–metastasis (TNM) staging (p < 0.05) in patients with TSCC." (PMID 33008143, 2020). "Based on the intersection of SAA receptors and TLR superfamily signature between human BC tissues and cell lines to exclude the tumor heterogeneity, TLR1 and TLR2 were highly expressed in both TNBC tissues and cell lines." (PMID 30728901, 2019). "In an animal model, synthetic bacterial lipoprotein (TLR1 agonist) induced tumor regression by increasing cytotoxic T lymphocyte function." (PMID 29416610, 2018). "We performed quantitative real-time PCR (qRT-PCR) to screen the expression levels of TLR1-10 in paired fresh tumor tissues and normal gastric tissue samples isolated from 10 patients with GC." (PMID 24030146, 2013). "TLR1 mRNA expression in the SCC tumor center was 5.49±1.21-fold higher (p<0.01) than in normal skin and also significantly higher than in the tumor center of BCCs (1.82±1.21, p<0.001)." (PMID 22808251, 2012). "We hypothesized that miRNAs act as TLR ligands where they block or inhibit pro-tumorigenic TLR1/7/8-mediated tumor growth and survival in CRC." (PMID 38987740, 2024). "TLR1/2-dependent cytokine induction was stronger in Black individuals (1.2-fold higher for IFN-β; P = 0.04) but was associated with survival independently of race or numbers of vaccine-induced tumor antigen–specific T cells." (PMID 39320053, 2024). "TLR1/2 exhibit duality in regulating MDSC behavior during tumor progression." (PMID 36911674, 2023). "In contrast to TLR2, TLR1 activation by RT has been shown to have tumor-promoting effects." (PMID 37112730, 2023). "Recent studies have shown that the activation of TLR1/2 signaling enhances the antitumor efficacy of CTLA-4 blockade, suggesting that TLR1/2 signaling participates in not only innate immunity against bacterial infection but also adaptive immunity to eradicate tumor cells." (PMID 37945630, 2023). "Taken together, these results showed that OXP can induce infiltration of effector/memory and cytotoxic immune cells to recognize and eradicate residual tumor cells via TLR1/2-mediated signaling, indicating that TLR1/2 is critical to enhance the therapeutic efficacy of immunogenic chemotherapy." (PMID 37945630, 2023). "Furthermore, systemic inhibition of TLR1/2 signaling markedly reduced the response to chemotherapy, leading to tumor regrowth." (PMID 37945630, 2023). "However, systemic administration of a TLR1/2 agonist significantly delayed tumor growth and increased the response to chemotherapy." (PMID 37945630, 2023). "Moreover, systemic inhibition of TLR1/2 dramatically reduced the tumor-infiltrating immune cells by OXP treatment, leading to poor therapeutic response to OXP." (PMID 37945630, 2023). "Moreover, LYN, MMP2, PRKCQ, and TLR1 can affect SKCM by influencing tumor cell metastasis, UV-induced cell injury, the NF-κB signaling pathway, and apoptosis." (PMID 36171883, 2022). "TLR1 intensity associated with no other clinicopathological parameters: gender, cancer stage, lymph-node ratio, tumor size, or microscopic invasion." (PMID 31314777, 2019). "In our whole population-based study, we retrieved 150 Finnish NPC cases and studied their tumour samples for TLR1, TLR2, TLR4, TLR5, TLR7, and TLR9 expressions by immunohistochemistry, and for the presence of EBV and high-risk HPVs with EBV RNA and HPV E6/E7 mRNA in situ hybridizations." (PMID 31238894, 2019). "To test our hypothesis, we first confirmed the TLR (TLR1-9) expression profiles in different types of tumor cells (primary or cell lines)." (PMID 25231413, 2014).
tumor (continued). "On the contrary, miRNA administration can also protect mice against tumour development in a TLR-1 NK-cell dependent manner, suggesting that immune signalling pathways might be cell type- or context-dependent." (PMID 25203514, 2014). "The up-regulation of RELA, AKT1, TLR1 and RAF1 and the down-regulation of MAPK9 and MAP3K8 were determined by RT-qPCR, indicating that the enhanced anti-tumor function may associate with T cell immune response and proliferation related Toll-like receptor-Akt-NF-κB signaling pathway." (PMID 35046962, 2021). "Finally, we explored whether TLR1/2 co-activation could improve cetuximab-mediated tumor elimination in tumor-bearing mice, as well as the infiltration of immune cells in the tumors." (PMID 34681717, 2021). "In mouse tumor models, research has demonstrated that adding adjuvants such as PAM3CSK4, a TLR2 and TLR1 agonist, to LNPs enhances humoral immunity, cellular responses, tumor inhibition, and survival rates." (PMID 40589473, 2025). "Studies have also shown that JAML activation enhances TLR1/2 expression on tissue-resident CD8+ T cells (CD8+ TRMs), which suppresses tumor progression and prolongs survival in tumor-bearing mice." (PMID 40636111, 2025). "IFN-β responses to TLR1/2 signaling correlated with increased numbers of IFN-γ producing T cells after broad, tumor antigen–independent stimulation." (PMID 39320053, 2024). "Defective TLR1 on DCs impaired their maturation ability by HMGB1 and reduced the secretion of IFNγ from T cells to eradicate tumor cells in vitro." (PMID 37945630, 2023). "With a few notable exceptions, stimulation of TLR1, TLR2 and TLR4 often leads to tumor-promoting effects by inducing immunosuppressive and antiapoptotic signals." (PMID 37112730, 2023). "In contrast, administration of a TLR1/2 agonist synergistically increased the benefit of OXP treatment and triggered a high density of tumor-infiltrating immune cells." (PMID 37945630, 2023). "Within the tumor microenvironment, we found that inhibition of TLR1/2 by the small molecule CU-CPT22 dramatically decreased the effect of OXP, leading to fewer tumor-infiltrating immune cells, including CD4+, CD8+ and IFNγ+ CD8+ cells." (PMID 37945630, 2023). "While most TLRs, such as TLR2, TLR4, TLR5, TLR7, and TLR9, play dual roles in carcinogenesis, TLR1 and TLR3 are largely tumor-suppressive, as demonstrated by induced apoptosis by TLR3 in human non-small-cell lung cancer cells." (PMID 36551308, 2022). "Combination treatment with the TLR1/2 ligand Pam3CSK4 and anti-CTLA4 mAb improved the anti-tumor immunity compared with anti-CTLA4 mAb alone." (PMID 35309296, 2022). "Despite the relatively evident tumor-suppressive roles of TLR1 and TLR3, controversies have been reported, such as the promoted tumor growth and cisplatin resistance observed in head and neck cancer cells as a result of activated TLR3 signaling." (PMID 36551308, 2022). "In KIRC, the results suggested that the mRNA levels of TLR1, TLR2, TLR3, TLR4, TLR7, and TLR8 were elevated in tumour tissues compared with normal kidney tissues." (PMID 34531911, 2021). "The expression of TLR1, TLR3, TLR5, TLR6, TLR7, TLR8, and TLR10 show significantly decreasing trends from normal tissues to surrounding tumor tissues and to tumor tissues." (PMID 34141706, 2021). "DaRT used in combination with the TLR9 agonist CpG, TLR3 agonist, poly I:C, or with the TLR1/2 agonist XS15, retarded tumor growth and increased tumor-rejection rates, compared with DaRT alone." (PMID 33503958, 2021). "DaRT used in combination with the TLR9 agonist CpG, or with the TLR1/2 agonist XS15 retarded tumor growth and increased tumor-rejection rates, compared to DaRT alone, curing 41% and 20% of the mice, respectively." (PMID 31637474, 2019).